CCL2 (C-C motif chemokine ligand 2)
Diseases named in the same sentence as CCL2 in open-access papers (continued):
Sharing a sentence is not in itself a finding about the gene and the disease.
pulmonary tuberculosis (25 papers, 2005 to 2025). A bacterial infection that affects the lungs and is caused by Mycobacterium tuberculosis. "CCL2-2518 GG and -362 CC genotypes were found to be associated with susceptibility to pulmonary tuberculosis and CCL2-2518AG and CCL2-362GC with resistance from PTB." (PMID 33381602, 2020). "The biallelic AC haplotype (CCL2-2518 A>G and -362 G>C) was noted to be a susceptible haplotype for pulmonary tuberculosis." (PMID 33381602, 2020). "A possible scenario where CCL2 AEI can be helpful is in resolving contradictory data obtained with the association of rs1024611G with pulmonary tuberculosis." (PMID 23166687, 2012). "In fact, higher levels of CCL2 were detected in the bronchoalveolar lavage (BAL) fluid of pulmonary TB patients and pleural fluid of HIV-1-infected patients, indicating the importance of this proinflammatory cytokine in HIV-M. tuberculosis coinfection." (PMID 32127457, 2020). "Increased release of chemokines, including IL-8/CXCL8, IP-10/CXCL10, MIG/CXCL9 and MCP-1/CCL2, has been observed in monocytes, alveolar macrophages and polymorphonuclear granulocytes in patients with pulmonary TB compared to healthy subjects." (PMID 24223729, 2013). "We observed that BCG-induced CCL2 responses in pulmonary tuberculosis were greater as compared to both extra-pulmonary tuberculosis and control groups." (PMID 16001981, 2005). "LPS stimulated CCL2 and TNFα responses were also raised in pulmonary tuberculosis as compared with extra-pulmonary tuberculosis patients." (PMID 16001981, 2005). "BCG- induced CCL2 was significantly greater in pulmonary tuberculosis as compared with extra-pulmonary at both 18 h (P = 0.001) and 48 h (P = 0.02, data not shown) post-stimulation." (PMID 16001981, 2005). "In response to LPS stimulation, patients with pulmonary tuberculosis showed increased CCL2 and TNFα responses as compared with the extra-pulmonary group." (PMID 16001981, 2005). "M. bovis BCG-induced ex vivo CCL2 secretion was significantly greater in pulmonary as compared with both extra-pulmonary tuberculosis patients and endemic controls." (PMID 16001981, 2005). "We observed raised CCL2 in pulmonary tuberculosis compared with controls in response to BCG stimulation." (PMID 16001981, 2005). "The coordinate increase in CCL2 and TNFα responses observed in the pulmonary TB group, may indicate active monocyte recruitment to the lungs which are likely to facilitate granuloma formation and localization of M. tuberculosis infection." (PMID 20041183, 2009). "Increased CCL2 in pulmonary tuberculosis may be related to localization of infection to the lung and may subsequently prevent disease dissemination." (PMID 16001981, 2005). "Increased CCL2 activation in pulmonary tuberculosis may result in a stronger cellular response as compared with extra-pulmonary tuberculosis patients, and this may contribute to the localization of infection to the pulmonary site." (PMID 16001981, 2005). "Raised CCL2 in pulmonary tuberculosis may lead to greater monocyte mediated immunity." (PMID 16001981, 2005). "CCL2/MCP-1, IL12p70, IFN-γ, TNF-α, and TGF-β were measured in serum samples of 120 pulmonary TB patients and 54 healthy controls." (PMID 33381602, 2020). "CXCL8 concentration was found to be elevated in fatal TB, increases in CCL2 were observed with disseminated and meningeal TB, and TGF-β increased in extrapulmonary TB in children compared to pulmonary TB." (PMID 32377537, 2020). "CCL2 level was observed to be positively correlated with IL12p70, IFN-γ and TNF-α, thus suggesting the immunological regulatory role of CCL2 against pulmonary tuberculosis." (PMID 33381602, 2020). "Serum levels of CCL2, CXCL8 and TNFα were measured in patients with pulmonary tuberculosis (N = 12), extra-pulmonary tuberculosis (N = 8) and BCG-vaccinated healthy volunteers (N = 12)." (PMID 16001981, 2005).
pulmonary tuberculosis (continued). "We determined circulating levels of CCL2, CXCL8 and TNFα in sera of pulmonary and extra-pulmonary tuberculosis patients and controls." (PMID 16001981, 2005). "Circulating levels of chemokines CXCL8, CCL2 and RANTES are raised in bronchoalveolar lavage fluid (BALF) and alveolar macrophages from pulmonary tuberculosis patients." (PMID 16001981, 2005).
atopic dermatitis (24 papers, 2011 to 2025). "In this respect, strong expression of CCL2 has been reported in the basal keratinocytes of atopic dermatitis patients, and expression of CCL7, which can attract basophils, eosinophils, mast cells and Th2 cells, can be induced by allergens in atopic skin." (PMID 27431613, 2016). "Moreover, MCP-1/CCL2 and IL-8 are closely linked to the onset and severity of chronic skin inflammation, with TARC/CCL17 levels showing a positive correlation with atopic dermatitis severity in affected individuals." (PMID 38786617, 2024). "In addition, it is necessary to determine whether IL6, CXCL8, and CCL2 levels are upregulated in dogs with atopic dermatitis and whether the symptoms of atopic dermatitis are alleviated when these cytokines are controlled." (PMID 39852930, 2025). "This aligns with previous studies demonstrating that IL-37b can inhibit the in vitro induction of pro-inflammatory cytokines (IL-6 and TNF-α) and chemokines (CXCL8, CCL2, and CCL5) related to atopic dermatitis." (PMID 40444012, 2025). "The reported list of inflammatory mediators found in atopic dermatitis includes S100A7, S100A8 S100A9, CCL2, CCL3, IL36A, IL36G, and IL36RN." (PMID 34925353, 2021). "A number of chemokines [CCL2, CCL3, CLL4, CCL8, CCL13, CCL19, chemokine (C-X-C motif) ligand (CXCL) 1, CXCL6, CXCL16] were upregulated in sensitized dogs after allergen challenge, similar to what is observed in human atopic dermatitis." (PMID 25098772, 2014). "Interestingly, OSB emissions significantly reduced the release of CCL2 from TCS‐stimulated and unstimulated keratinocytes and slightly reduced IL‐1β from TCS‐stimulated keratinocytes, confirming no or rather beneficial effects of OSB‐specific VOCs in a human in vitro atopic dermatitis model." (PMID 40114338, 2025).
triple-negative breast carcinoma (24 papers, 2016 to 2025). An invasive breast carcinoma which is negative for expression of estrogen receptor (ER), progesterone receptor (PR), and human epidermal growth factor receptor 2 (HER2). "Targeted gene silencing of CCL2 inhibits triple negative breast cancer progression by blocking cancer stem cell renewal and M2 macrophage recruitment." (PMID 35585513, 2022). "We examined associations of CCL2, CCR2, phospho-SMAD3 and phospho-p42/44MAPK with molecular subtype including: luminal A and B, HER2+ and triple negative breast cancers, which were identified using clinical guidelines on ER, PR, HER2 and Ki67/PCNA expression." (PMID 33888841, 2021). "We next tested the effect of CCL2 on the proliferation of mouse triple negative breast cancer 4T1 cells by CCK8 assay and colony formation assay." (PMID 33244467, 2020). "There are reports that the tumor promoting effect of CCL2 applies to both ER+ and triple negative breast cancers." (PMID 28143493, 2017). "Furthermore, it was demonstrated that both the transcription and secretion levels of CCL2 were elevated in the triple-negative breast cancer cell line." (PMID 39703847, 2024). "Since CCL2 secreted by M2 macrophages is known to be associated with paclitaxel resistance in triple-negative breast cancer (TNBC), we next examined whether CCL2 secreted by THP-1 cells co-cultured with K2A-1 is involved in the paclitaxel resistance mechanism." (PMID 37821959, 2023). "A recent study uncovered a direct impact of RXRα in the TGF-β-dependent regulation of the CCL2 gene in triple-negative breast cancer cells, indicating that physical interaction might occur between these proteins." (PMID 36078038, 2022).
non-small cell lung carcinoma (23 papers, 2010 to 2025). A group of at least three distinct histological types of lung cancer, including non-small cell squamous cell carcinoma, adenocarcinoma, and large cell carcinoma. "Polymorphism at rs3760396 of CCL2 genes is associated with the prognosis of non-small cell lung cancer (NSCLC)." (PMID 27145753, 2016). "Thus, the same genetic variation of CCL2 gene can affect both the risk of occurrence of adenosquamous cell lung carcinoma and the outcome of non-small cell lung cancer." (PMID 27145753, 2016). "ALKBH5 promotes non-small cell lung cancer progression by regulating cancer and tumor-associated macrophage behavior through the JAK2/p-STAT3 pathway and the expression of CCL2 and CXCL10, respectively." (PMID 38872221, 2024). "Their findings suggest that the CCL2/CCR2 axis enhances the migration of CAR-T cells into brain metastases of non-small cell lung cancer." (PMID 36359834, 2022). "A clinical trial reported that erlotinib, an EGFR inhibitor approved by the Food and Drug Administration, decreased serum CCL2 levels in non-small-cell lung cancer (NSCLC) patients." (PMID 34386431, 2021). "CCL2 expression has been shown to be increased in activated human PBMCs from non-small cell lung cancer patients." (PMID 27058904, 2016). "Vaccine immunotherapy against an HPV16 E7 expressing non-small cell lung cancer (NSCLC) line has been shown to be more effective with an anti-CCL2 blocking antibody." (PMID 25340820, 2014). "Furthermore, CCL2 levels have been suggested to be a potential marker for disease surveillance following treatment of non-small cell lung cancer with anlotinib, a tyrosine receptor kinase inhibitor, which was found to suppress xenograft angiogenesis through CCL2 inhibition." (PMID 37964011, 2023). "In non-small-cell lung cancer (NSCLC), ALKBH5 mediated m6A modification of JAK2 mRNA, activated the JAK2/p-STAT3/CCL2/CXCL10 axis, leading to the recruitment of PD-L1 + TAMs and promoting M2 macrophage polarization." (PMID 39987091, 2025). "CCL2 promotes the metastasis and EMT of non-small cell lung cancer through the PI3K/AKT/mTOR axis and autophagy signaling pathways." (PMID 40229278, 2025). "In non-small cell lung cancer (NSCLC), CCL2 reduces E-cadherin levels and upregulates vimentin, MMP-2 and MMP-9 protein levels through PI3K/Akt/mTOR to activate EMT." (PMID 41341593, 2025). "Additionally, it was shown that other pathways are involved in the mediation of CCL2 secretion and TAM recruitment, e.g., upregulation of CtBP1 promoted activation of CCL2 secretion and, as a result, infiltration of TAMs in non-small cell lung cancer (NSCLC)." (PMID 33919517, 2021). "CCL2 is upregulated in some solid tumors, such as malignant pleural mesothelioma (MPM) and non-small cell lung carcinoma (NSCLC)." (PMID 40148310, 2025).
Pleural effusion (23 papers, 2005 to 2025). The presence of an excessive amount of fluid in the pleural cavity. "The expression of chemokines in our data and TCGA revealed that CCL2 was the highest expressed chemokine in all sample types (cell lines, pleural effusion and pleura)." (PMID 35637530, 2022). "Noteworthy, CCL2, a key monocyte chemoattractant, is significantly elevated in both pleural effusion and serum of MPM patients in advanced stages of the disease." (PMID 33922336, 2021). "Additionally, cytokines promoting the M2 differentiation, namely IL-34, macrophage colony stimulating factor (M-CSF) and C-C motif chemokine ligand 2 (CCL2) have been found to be elevated in tumor specimens or pleural effusion of MPM patients." (PMID 33562138, 2021). "CCL2 is upregulated in pleural effusion and serum from MPM patients compared to benign pleural effusion or pleural effusion from other malignancies and serum from healthy volunteers, respectively." (PMID 34249695, 2021). "Moreover, the levels of CCL2 are elevated in the MPM pleural effusion on MPM patients compared to benign tissues, and CCL2 levels in the serum were elevated in late-stage MPM patients, suggesting their importance in MPM progression." (PMID 33233664, 2020). "High levels of CCL2 are present in the pleural effusions of mesothelioma patients, however, CCL2 has not been examined in the serum of mesothelioma patients." (PMID 31823764, 2019).
pulmonary hypertension (23 papers, 2014 to 2025). Increased pressure within the pulmonary circulation due to lung or heart disorder. "Of these chemokines and chemokine receptors, Ccl2, Ccl7, Ccl20, Ccl21, Cxcl13, Cxcl4, Ccr6 and Ccr7 have already been demonstrated to be associated with pulmonary hypertension." (PMID 32176619, 2020). "This schematic illustrates the core mechanism in the pathogenesis of pulmonary arterial hypertension: Pulmonary vascular injury activates lung macrophages, releasing inflammatory mediators such as CCL2/CCL7, IL-1β/IL-6, and mitochondrial DAMPs into the circulatory system." (PMID 41479889, 2025).
renal failure (23 papers, 2009 to 2025). "To test for a causal link between FMD-induced CCL2 decline, reduced renal monocyte recruitment, and kidney failure, we treated FMD or ad lib BALB/c male mice with a CCR2 inhibitor (CCR2i) after AA injection." (PMID 40755453, 2025). "The -2518A allele (CCL2) was reported to be associated with kidney failure in Korean type 2 DM patients." (PMID 19357773, 2009). "At the same time, the second one refers to the CCL2 role in tubulointerstitial inflammation during kidney failure by inducing cytokine and adhesion molecule production." (PMID 37901222, 2023). "Fetal urine chemokines CCL2 (MCP-1), CXCL9 (MIG), and CCL4 (MIP-1β) were identified as predictive of postnatal kidney failure in fetuses with PUV from the discovery cohort." (PMID 39614902, 2025).
retinal detachment (23 papers, 2008 to 2024). An eye emergency condition which may lead to blindness if left untreated. "It has also been shown that photoreceptor loss after retinal detachment or light-induced degeneration can be attenuated by ablation of CCL2 or CCR2 signalling by reducing recruitment of ED1 and Iba1 positive cells." (PMID 23232206, 2013). "It has been shown that the cytotoxic effect of CCL2 is probably mediated by oxidative stress in retinal detachment–induced photoreceptor apoptosis." (PMID 33148888, 2020). "In summary, we found that following retinal detachment, monocyte infiltration into the vitreous and vitreo-retinal interface is rapid, and sets off a cascade of downstream cytokine events that further escalates immune response, like retinal CCL2 expression." (PMID 28645275, 2017). "CCL2 has been shown to play a role in retinal neovascularization and retinal detachment." (PMID 25329075, 2014). "In the retina, an investigation in experimental retinal detachment using Ccl2−/− mice and Ccl2-specific antibody neutralization noted a substantial decrease in the recruitment of parenchymal microglia to the ONL following detachment, in conjunction with reduced photoreceptor death." (PMID 22992301, 2012).
systemic sclerosis (23 papers, 2006 to 2025). A chronic disorder, possibly autoimmune, marked by excessive production of collagen which results in hardening and thickening of body tissues. "Of note, CCL2 levels were correlated with the extent of skin fibrosis in systemic sclerosis, a pathogenic feature also triggered by IL11 expression in SMCs." (PMID 31917819, 2020). "On the other hand, some studies have shown an association between interstitial lung involvement and levels of MCP-1/CCL2 in patients with systemic sclerosis." (PMID 37047772, 2023). "GDF-15 was directly involved in the production of proinflammatory cytokines and chemokines, such as IL-6 and CCL2 in bleomycin-induced mice and systemic sclerosis (SSc) patients with lung involvement." (PMID 35784345, 2022). "Using ultrasound, they found, compared to control, stretching reduced skin thickness, increased subcutaneous tissue mobility, and downregulated genes related to systemic sclerosis in mice (Ccl2 and Adam8)." (PMID 35648793, 2022). "As expected,CCL2, a chemokyne involved in such fibrogenic diseases as systemic sclerosis, increased its expression in Schwann cells and in the infiltratingmacrophages of leprosy-affected peripheral nerves." (PMID 31389520, 2019). "In systemic sclerosis (SSc), IL-22 synergistically works with TNFα to induce the expression of IL-8 and CCL2 in skin fibroblasts, while the simultaneous stimulation of TGF-β1 and IL-17A can lead to an up-regulation of IL-6 expression in fibroblasts from affected skin by nearly a hundredfold." (PMID 35967331, 2022). "The lower percentage of CCR2+Tfh in the patients could indicate CCL2-directed migration of such cells into lymphoid tissues and/or target organs in systemic sclerosis." (PMID 33407866, 2021). "This SNP was reported to impact CCL2 expression in patients with Systemic Sclerosis (SSc)." (PMID 30123371, 2018). "CCL2, a ligand for CCR2, is elevated in early systemic sclerosis and is a biomarker for progression of interstitial lung disease in these patients." (PMID 33407866, 2021). "In patients with systemic sclerosis, CD14-positive monocytes show elevated expression of versican that is accompanied by elevated expression of CCL2 [also known as Monocyte Chemoattractant Protein 1 (MCP-1)]." (PMID 32265939, 2020). "This points to an inflammatory gene expression signature in the skin that is reminiscent of that seen in systemic sclerosis, since IL6, CCL2, and CCL5 are elevated in the serum of patients." (PMID 31917819, 2020). "Similarly, in systemic sclerosis (skin fibrosis), the levels of circulating CCL2, CCL3, and CCL5 chemokines were significantly higher in patients with systemic sclerosis than in controls." (PMID 33519923, 2020).